DAXX (death domain associated protein)
Description:
Transcription corepressor known to repress transcriptional potential of several sumoylated transcription factors. Down-regulates basal and activated transcription. Its transcription repressor activity is modulated by recruiting it to subnuclear compartments like the nucleolus or PML/POD/ND10 nuclear bodies through interactions with MCSR1 and PML, respectively. Seems to regulate transcription in PML/POD/ND10 nuclear bodies together with PML and may influence TNFRSF6-dependent apoptosis thereby. Inhibits transcriptional activation of PAX3 and ETS1 through direct protein-protein interactions. Modulates PAX5 activity; the function seems to involve CREBBP. Acts as an adapter protein in a MDM2-DAXX-USP7 complex by regulating the RING-finger E3 ligase MDM2 ubiquitination activity. Acts as a histone chaperone that facilitates deposition of histone H3.3. Acts as a targeting component of the chromatin remodeling complex ATRX:DAXX which has ATP-dependent DNA translocase activity and catalyzes the replication-independent deposition of histone H3.3 in pericentric DNA repeats outside S-phase and telomeres, and the in vitro remodeling of H3.3-containing nucleosomes. Does not affect the ATPase activity of ATRX but alleviates its transcription repression activity. Upon neuronal activation associates with regulatory elements of selected immediate early genes where it promotes deposition of histone H3.3 which may be linked to transcriptional induction of these genes. Required for the recruitment of histone H3.3:H4 dimers to PML-nuclear bodies (PML-NBs); the process is independent of ATRX and facilitated by ASF1A; PML-NBs are suggested to function as regulatory sites for the incorporation of newly synthesized histone H3.3 into chromatin. In case of overexpression of centromeric histone variant CENPA (as found in various tumors) is involved in its mislocalization to chromosomes; the ectopic localization involves a heterotypic tetramer containing CENPA, and histones H3.3 and H4 and decreases binding of CTCF to chromatin. Proposed to mediate activation of the JNK pathway and apoptosis via MAP3K5 in response to signaling from TNFRSF6 and TGFBR2. Interaction with HSPB1/HSP27 may prevent interaction with TNFRSF6 and MAP3K5 and block DAXX-mediated apoptosis. In contrast, in lymphoid cells JNC activation and TNFRSF6-mediated apoptosis may not involve DAXX. Shows restriction activity towards human cytomegalovirus (HCMV). Plays a role as a positive regulator of the heat shock transcription factor HSF1 activity during the stress protein response.
Synonyms: EAP1; BING2; DAP6
Tractability: Small molecule: a structure with a bound ligand is known. PROTAC: UniProt records ubiquitination sites on it; ubiquitination databases record sites on it; its protein half-life has been measured.
Gene: Protein-coding gene on chromosome 6 (33,318,558 to 33,323,259, reverse strand). Ensembl gene ENSG00000204209.
Subcellular location: Cytoplasm; Nucleus, nucleoplasm; Nucleus, PML body; Nucleus, nucleolus; Chromosome, centromere; Nucleus (Isoform beta); Nucleus (Isoform gamma)
Subcellular location (Human Protein Atlas): Nuclear bodies; Nucleoplasm
Pathways (Reactome):
Disease: Defective Inhibition of DNA Recombination at Telomere Due to ATRX Mutations; Defective Inhibition of DNA Recombination at Telomere Due to DAXX Mutations; Dengue virus modulates apoptosis; HCMV Early Events
Cell Cycle: Inhibition of DNA recombination at telomere
Metabolism of proteins: SUMOylation of transcription cofactors
Gene Ontology:
Molecular function: ATP-dependent H3-H4 histone complex chaperone activity; enzyme binding; histone binding; molecular condensate scaffold activity; nuclear androgen receptor binding; protein binding; protein kinase activator activity; protein kinase binding; RNA polymerase II-specific DNA-binding transcription factor binding; transcription coactivator activity; transcription corepressor activity; transcription regulator inhibitor activity; ubiquitin protein ligase binding; heat shock protein binding
Biological process: androgen receptor signaling pathway; cellular response to cadmium ion; cellular response to copper ion; cellular response to diamide; cellular response to heat; cellular response to sodium arsenite; cellular response to unfolded protein; DNA replication-dependent chromatin disassembly; extrinsic apoptotic signaling pathway via death domain receptors; JNK cascade; negative regulation of DNA-templated transcription; negative regulation of gene expression; neuron intrinsic apoptotic signaling pathway in response to oxidative stress; regulation of DNA-templated transcription; regulation of gene expression; regulation of protein ubiquitination; subtelomeric heterochromatin formation; chromatin remodeling; nucleosome assembly; regulation of apoptotic process; positive regulation of DNA-templated transcription
Cellular component: chromosome, centromeric region; cytoplasm; nuclear body; nucleoplasm; nucleus; PML body; cytosol; chromosome, telomeric region; nucleolus
Genetic constraint (gnomAD): Loss-of-function variants: 23 observed, 62.15 expected, observed/expected ratio (o/e) 0.37, 90% interval 0.26 to 0.52. The upper end of that interval is the gene's LOEUF score, 0.52, which puts it in group 2 of 6, group 1 being the genes least tolerant of losing a copy. Missense variants: 799 observed, 955.95 expected, observed/expected ratio (o/e) 0.84, 90% interval 0.79 to 0.89. Synonymous variants: 346 observed, 376.84 expected, observed/expected ratio (o/e) 0.92, 90% interval 0.84 to 1.
Cancer hallmarks: genome instability and mutations (promotes); escaping programmed cell death (suppresses); escaping programmed cell death (promotes); genome instability and mutations (suppresses); invasion and metastasis (promotes); proliferative signalling (promotes)
Homologues: Orthologues: chimpanzee DAXX (99% identical), dog DAXX (90% identical), pig DAXX (86% identical), rabbit DAXX (81% identical), mouse Daxx (72% identical), rat Daxx (72% identical), guinea pig DAXX (67% identical), tropical clawed frog daxx (39% identical), zebrafish daxx (34% identical), Drosophila melanogaster Daxx (22% identical).
Diseases named in the same sentence as DAXX in open-access papers:
DAXX is named in the same sentence as 122 diseases in open-access papers, as found by Europe PMC text mining. Sharing a sentence is not in itself a finding about the gene and the disease. The quoted sentences say what the papers report.
pancreatic neuroendocrine tumor (47 papers, 2013 to 2026). Pancreatic endocrine tumor, also known as pancreatic neuroendocrine tumor (PNET), describes a group of endocrine tumors originating in the pancreas that are usually indolent and benign, but may have the potential to be malignant. "Next, we found that mutations in MEN1, PTEN and ATRX or DAXX co-occur with a high statistical likelihood, suggesting that co-mutation of those genes is one of the core determinants of pancreatic neuroendocrine tumors pathogenesis." (PMID 38609433, 2024). "Patients with primary pancreatic NETs and loss of DAXX, ATRX, ARID1, and/or CDKN2A had reduced survival times." (PMID 37387515, 2023). "The exome sequencing of ten sporadic pancreatic neuroendocrine tumors (PanNETs) identified recurrent and mutually exclusive loss-of-function mutations in DAXX and ATRX for the first time." (PMID 35976056, 2022). "In NET G3, which is most frequently occurring in the pancreas, most alterations were also seen in pancreatic primaries, including mutations in MEN1 (33%), ATRX (25%) and DAXX (25%; within the subgroup of pancreatic NET G3)." (PMID 34647903, 2021). "Chromosome instability and reduced survival have been associated with the ATRX and DAXX mutations in pancreatic NETs as well." (PMID 31527438, 2019). "Furthermore, recent studies discussed potential prognostic utility of mutations in alpha-thalassemia/mental retardation X-linked chromatin remodeler (ATRX) and death-domain-associated protein (DAXX) genes in metastatic disease in pancreatic NETs." (PMID 38893179, 2024). "The genes encoding the chromatin remodeling complex DAXX:ATRX are frequently mutated in pancreatic neuroendocrine tumors; however, the underlying mechanisms of how mutations contribute to tumorigenesis are only partially understood, in part because of the lack of relevant preclinical models." (PMID 35976056, 2022). "In addition, we also knocked down DAXX, as both proteins act together as chromatin remodelers and one or both is mutated in pancreatic neuroendocrine tumors with an ALT-like phenotype." (PMID 26001292, 2015). "Furthermore, mutations of the TrxG component multiple endocrine neoplasia type 1 (MEN1) are found in neuroendocrine pancreatic tumors and is mutually exclusive with DAXX and ATRX mutations, suggesting similar functional roles." (PMID 23760585, 2013). "Genomic studies focusing on pancreatic NETs highlighted mutations in MEN1, DAXX, ATRX, and targets in mTOR pathway." (PMID 41483302, 2026). "Based on prior data, the most prevalent mutations in pancreatic neuroendocrine tumors include those in MEN1 (44%), DAXX/ATRX (43%) 17, 18, and genes related to the mTOR pathway." (PMID 41323792, 2025). "In neuroendocrine pancreatic tumors, DAXX, the histone chaperone partner of ATRX, is frequently altered in ALT + cases, and has similarly been implicated in pHGG." (PMID 41422096, 2025). "Recent sequencing studies revealed that pancreatic neuroendocrine tumors (PanNETs) are driven by somatic loss-of-function mutations in epigenetic regulators, with recurrent mutations in MEN1 (38%), DAXX (23%), and ATRX (10%)." (PMID 37633949, 2023). "Inactivating somatic mutations in ATRX, DAXX, and MEN1 represent the major mutations encountered in pancreatic NETs, but are much less frequent in their thoracopulmonary counterparts, indicating distinct site-dependent genetic pathways driving these tumors." (PMID 36690805, 2023). "First, DAXX and ATRX mutations are mutually exclusive in pancreatic neuroendocrine tumors, indicating their shared function is required for tumor suppression." (PMID 37633949, 2023). "Although the loss of ATRX/DAXX and ALT in pancreatic NET is generally associated with tumor aggressiveness and reduced progression-free survival, these features are associated with better overall survival in the sub-cohort of metastatic patients." (PMID 33555458, 2021).
pancreatic neuroendocrine tumor (continued). "There is a strong correlation between ATRX and DAXX mutations and an alternative lengthening of telomeres (ALT) phenotype in pancreatic NET." (PMID 33555458, 2021). "Pancreatic NET also exhibit recurrent mutations in a relatively limited number of genes, including the tumor suppressor gene MEN1, as well as ATRX and DAXX, genes implicated in chromatin remodeling." (PMID 32477464, 2020). "In pancreatic neuroendocrine tumors (PanNETs) ATRX, DAXX, and MEN1 are commonly mutated (A-D-M mutant PanNETs)." (PMID 30315258, 2018). "Pancreatic NETs have variations in DAXX, ATRX, PTEN, and TSC2, whereas GI-NETs have identified CDKN1B and RASSF1A as the recurrent mutations." (PMID 29255447, 2017). "Pancreatic neuroendocrine tumors are also characterized by recurrent mutations in a relatively limited number of genes, which include tumor suppressor gene MEN1, as well as ATRX and DAXX, genes implicated in chromatin remodeling." (PMID 28903345, 2017). "Recently, pancreatic NETs were characterized as having recurrent somatic mutations in MEN1, DAXX, ATRX, TSC, and PTEN on the basis of exome sequencing of 10 pancreatic NETs." (PMID 26684240, 2016). "ATRX is also found mutated in neuroblastoma, while both DAXX and ATRX are mutated in neuroendocrine tumors of the pancreas." (PMID 23760585, 2013). "Furthermore, the gene panel is restricted to 73 genes failing to test for MEN1, ATRX or DAXX, which are clinically important in pancreatic NET." (PMID 32477464, 2020). "Furthermore, in pancreatic neuroendocrine tumors, aberrant ATRX and DAXX expression was associated with lymph node metastasis and distant metastasis by causing the abnormal lengthening of telomeres, and was also associated with shorter disease-free survival and disease-specific survival." (PMID 34272397, 2021). "Pancreatic NETs frequently exhibit changes in genes such as MEN1, DAXX, ATRX, TSC1, TSC2, CDKN1A, and CDKN1B, along with alterations in CDKN2A and SETD2 in metastatic lesions." (PMID 41426335, 2025). "The authors also found that pancreatic NETs exhibit recurrent genetic inactivation of MEN1, ATRX, and DAXX and the activation of the PI3K/mTOR pathway." (PMID 40026252, 2025). "Certain mutations in KLKB1, mutated in one of five CT-pNENs, cause prekallikrein deficiency, and KLKB1 was mutually exclusive with ATRX, DAXX, and MEN1 of pancreatic neuroendocrine tumors (PanNets)." (PMID 37771441, 2023). "Hallmarks of NET G1/G2 are loss of chromosome 18, inactivation of CDKN1/APC, and gain of chromosomes 4, 5, and 14 in NET of the small intestine and inactivation of MEN1/chromosome 11, DAXX/ATR, and PTEN/TSC2 in pancreatic NET." (PMID 33228231, 2020).
pancreatic neuroendocrine tumor (continued). "Here, using paediatric glioma and pancreatic neuroendocrine tumor cell lines, we identify a novel ATRX-independent function for DAXX in promoting genome stability by preventing transcription-associated R-loop accumulation and DNA double-strand break formation at centromeres." (PMID 38038252, 2024). "The most frequent gene alterations in pancreatic NETs were MEN1 and DAXX/ATRX." (PMID 37387515, 2023).
α-thalassemia (43 papers, 2013 to 2025). "DAXX forms a complex with the ATRX (α-thalassaemia with mental retardation, X-linked) chromatin remodeller, and this complex is also frequently mutated in gliomas, strongly suggesting that the ATRX/DAXX/H3.3 axis is pivotal in these cancers." (PMID 38066546, 2023). "PML is a major component of ND10 repositories that encages intrinsic chromatin remodeling proteins that include sp100, the death domain associated protein hDAXX and alpha-thalassemia/mental retardation syndrome X-linked protein ATRX." (PMID 34603296, 2021). "Mutations in ATRX (α-thalassemia/mental retardation syndrome X-linked) and DAXX (death domain associated protein) have been frequently observed in pNETs." (PMID 34680266, 2021). "Dysfunction of the α-thalassemia/mental retardation syndrome X-linked (ATRX)/death-associated protein 6 (DAXX) complex is known to result in ALT along with more widespread genomic destabilization." (PMID 31960234, 2020). "Mutations in ATRX (α-thalassaemia/mental retardation syndrome X-linked) and DAXX (death-domain associated protein) genes that encode two subunits of a chromatin remodeling complex required for H3.3 incorporation at pericentric heterochromatin and telomeres, were identified in 31% of pediatric GBMs." (PMID 24202337, 2013). "Notably, the authors also described a strong association of ALT with the mutational status of two chromatin remodeling genes, whose mutations are usually mutually exclusive: death domain-associated protein (DAXX) and α-thalassemia/mental retardation X-linked (ATRX) genes [14••]." (PMID 34269919, 2021). "Genomic analysis has revealed that NENs show alterations in chromatin remodeling genes, such as MEN1, DAXX (death domain-associated protein), and ATRX (α thalassemia/mental retardation syndrome X-linked)." (PMID 39201255, 2024). "The most frequently described somatic mutations in sporadic PanNETs occur in the following genes: MEN1, DAXX (death domain associated protein), ATRX (α-thalassemia/mental retardation syndrome X-linked), and genes related to the mTOR signal pathway." (PMID 39768544, 2024). "For sporadically occurring PNETs, MEN1, DAXX (death domain associated protein), ATRX (α-thalassemia/mental retardation syndrome X-linked), and genes related to the mammalian target of rapamycin (mTOR) pathway harbor commonly identified somatic alterations." (PMID 38279330, 2024). "Generally, ALT is activated by loss-of-function (LOF) genetic alterations in the chromatin remodelers α thalassemia-mental retardation, X linked (ATRX) and death domain-associated protein 6 (DAXX)." (PMID 39224814, 2024). "The most common mutations reported in ALT cancers and cell lines are mutations in genes encoding for α-thalassemia/mental retardation syndrome X-linked (ATRX) and death-domain-associated protein (DAXX)." (PMID 38752489, 2024). "The ALT pathway is associated with the inactivation of a-thalassemia/mental retardation syndrome and X-linked (ATRX) and death-domain-associated proteins (DAXX)." (PMID 39408829, 2024). "Mutations in the MEN1, death-domain-associated protein (DAXX), and α thalassemia/mental retardation syndrome X-linked (ATRX) genes were found in 44.1%, 25%, and 17.6% of patients, respectively." (PMID 37190177, 2023). "The mutation or loss of α-thalassemia/mental retardation syndrome, X-linked (ATRX) and death domain-associated protein (DAXX) seems to be the key determinant of the emergence and maintenance of ALT." (PMID 34330324, 2021). "Mutations in the α-thalassemia/mental retardation syndrome X-linked (ATRX) and death-domain associated protein (DAXX) genes have become intimately linked to the ALT phenotype." (PMID 34069193, 2021). "In the nucleus, DAXX interacts with transcription factors, epigenetic modifiers, and chromatin-remodeling proteins such as the transcription regulator ATRX—the α-thalassemia/mental retardation syndrome X-linked ATP-dependent helicase II." (PMID 33525665, 2021).